RNU4-61P (RNA, U4 small nuclear 61, pseudogene)
Gene: Small nuclear RNA gene on chromosome 1 (48,447,936 to 48,448,042, forward strand). Ensembl gene ENSG00000223175.
Homologues: Orthologues: chimpanzee U4 (100% identical), guinea pig U4 (58% identical). Paralogues in human: RNU4-53P (70% identical), RNU4-40P (69% identical), RNU4-89P (67% identical), RNU4-91P (66% identical), RNU4-36P (65% identical), RNU4-12P (64% identical), RNU4-42P (64% identical), RNU4-4P (64% identical), RNU4-67P (64% identical), RNU4-7P (64% identical), RNU4-86P (64% identical), U4 (64% identical), and 81 more.